IGKC (immunoglobulin kappa constant)
Description:
Constant region of immunoglobulin light chains. Immunoglobulins, also known as antibodies, are membrane-bound or secreted glycoproteins produced by B lymphocytes. In the recognition phase of humoral immunity, the membrane-bound immunoglobulins serve as receptors which, upon binding of a specific antigen, trigger the clonal expansion and differentiation of B lymphocytes into immunoglobulins-secreting plasma cells. Secreted immunoglobulins mediate the effector phase of humoral immunity, which results in the elimination of bound antigens. The antigen binding site is formed by the variable domain of one heavy chain, together with that of its associated light chain. Thus, each immunoglobulin has two antigen binding sites with remarkable affinity for a particular antigen. The variable domains are assembled by a process called V-(D)-J rearrangement and can then be subjected to somatic hypermutations which, after exposure to antigen and selection, allow affinity maturation for a particular antigen.
Synonyms: HCAK1; IGKCD; Km
Gene: Immunoglobulin constant (C) gene on chromosome 2 (88,857,161 to 88,857,683, reverse strand). Ensembl gene ENSG00000211592.
Subcellular location: Secreted; Cell membrane
Subcellular location (Human Protein Atlas): Cytosol; Vesicles; Predicted to be secreted
Gene-disease validity (ClinGen):
ClinGen rates the evidence that IGKC causes each of these diseases.
recurrent infections associated with rare immunoglobulin isotypes deficiency (autosomal recessive): Limited.
Homologues: Orthologues: chimpanzee IGKC (98% identical), macaque IGKC (71% identical), mouse Igkc (60% identical). Paralogues in human: IGLC3 (37% identical), IGLC2 (36% identical), IGLC7 (36% identical), IGLC1 (35% identical), IGLL1 (35% identical), IGLL5 (35% identical), IGHG1 (29% identical), IGHG2 (29% identical), IGHG4 (29% identical), IGHG3 (28% identical), IGHM (24% identical), IGHA2 (22% identical), and 65 more.
Diseases named in the same sentence as IGKC in open-access papers:
IGKC is named in the same sentence as 51 diseases in open-access papers, as found by Europe PMC text mining. Sharing a sentence is not in itself a finding about the gene and the disease. The quoted sentences say what the papers report.
breast carcinoma (19 papers, 2012 to 2025). "IGKC (immunoglobulin kappa constant) has previously been linked to metastasis-free survival in breast cancer and identified as a prognostic marker in non-small-cell lung cancer and colorectal cancer." (PMID 41149858, 2025). "IGKC has been found to be associated with favorable prognosis in breast cancer, CRC, and non‐small cell lung cancer." (PMID 33463049, 2021). "Some studies provide evidence that high expression of a B cell/plasma cell metagene is associated with favorable prognosis in breast cancers; others propose that expression level of IGKC alone has equivalent predictive and prognostic value." (PMID 29899747, 2018). "IGKC has been validated as a prognostic and therapeutic biomarker in human breast cancer and other cancers." (PMID 37223018, 2023). "IGKC (immunoglobulin kappa C), expressed in plasma cells, has been identified as one of the top genes of a prognostic B cell metagene in breast cancer, correlated with favorable prognosis and response to chemotherapy." (PMID 36424614, 2022). "IGKC is an important component of immunoglobulins, which are involved in innate and adaptive immunity, and is an effective prognostic biomarker for breast cancer and non-small cell lung carcinoma (NSCLC)." (PMID 35646951, 2022). "We examined the relevance of immunoglobulin kappa C (IGKC), an important part of the humoral immune system, in early breast cancer." (PMID 34298839, 2021). "Of them, a set of genes related to immune function, such as CXCL13, IGHM, IGLL3P, IGJ and IGKC, were up-regulated in young patients with breast cancer." (PMID 25990390, 2015). "IGKC (Ig κ chain C region) participates in humoral immune response, which has been reported to play key roles in non-small cell lung cancer and breast cancer." (PMID 25318463, 2014). "These investigators identified the immunoglobulin G kappa chain (IGKC) as an immunologic biomarker of prognosis and response to chemotherapy in hundreds of patients with breast cancer, non-small lung cancer, and CRC." (PMID 23730621, 2013). "Notably, these top-ranked genes have established associations with breast cancer, with studies indicating that the expression patterns of FN1 and IGKC correlate with patient survival and clinical outcomes." (PMID 38145948, 2023). "The IGKC gene mutation rs232230 (C- > G) (IGKC*04 in the IMGT database) results in a nonsynonymous variant (V- > L) that is a risk factor in Helicobacter pylori infection in gastric cancer and age in breast cancer (odds ratio 1.64 and 1.94, respectively)." (PMID 34120151, 2021). "We show that an increased amount of IGKC in the tumor is linked to longer distant metastasis-free survival, especially in patients whose breast cancer does not express hormone receptors or human epidermal growth factor receptor-2." (PMID 34298839, 2021). "Cluster C0 and C1 highly expressed immunoglobulin kappa C (IGKC), which is associated with good prognosis in a variety of tumors, including CRC, breast cancer, and non-small cell lung cancer, implying that humoral immunity may also play an essential role in antitumor immunity." (PMID 36551288, 2022). "In addition, IGKC is regarded as a prognostic marker in breast cancer, which means that the genotype of the light chain region may be related to the immune status and function of B cells." (PMID 34658852, 2021). "Kaplan-Meier analysis, univariate and multivariate Cox analysis illustrated that a stronger expression of IGKC was significantly associated with improved breast cancer specific survival and DFS independent of other prognostic factors in the entire cohort of node-negative breast cancer patients." (PMID 23028600, 2012). "Building on these results, we described that immunoglobulin Kappa C (IGKC), a single gene of this B cell metagene, was found to be a representative marker and showed a favourable metastasis-free survival (MFS) in breast cancer both at the ribonucleic acid (RNA) and at the protein level." (PMID 23028600, 2012).
COVID-19 (5 papers, 2021 to 2024). A disease caused by infection with severe acute respiratory syndrome coronavirus 2. "Among these down-regulated genes in COVID-19 group, we found IGKC, IGHG1 and IGHV1-2, encoding for immunoglobulin constant and variable chains related to immune response." (PMID 34615949, 2021). "Specifically, signatures of plasma cells (IGHG3, IGKC, IGHM, JCHAIN, IGHG2, IGKV4-1, IGLV3-1, IGHA1), activated fibroblasts (COL1A1, COL1A2, COL3A1), inflammatory cytokines (CXCL9, CCL18) and complement factors (C1QB, C1QC) dominated the DE genes for the COVID-19 lung sections." (PMID 37858234, 2023).
lung cancer (5 papers, 2012 to 2025). A malignant neoplasm involving the lung. "To validate the sequencing results, we selected three genes (MUC1, MYO6, and IGKC) among the 11 important molecular marker candidates for silent transient cell line construction and transferred silent MUC1 and MYO6 into lung cancer cell line A-549, and silent IGKC into normal lung cell HPAEC." (PMID 39991571, 2025). "Notably, elevated expression levels of production of immunoglobulin-related genes IGHG4, IGKC, IGLC2, IGHG3, and PLAU were detected in the SPP1-Mφ cluster, suggesting the proinflammatory and anti-tumor functions of this cluster in lung cancer." (PMID 36008393, 2022). "IGKC, Ig kappa chain V-IV region Len, protein IGKV2-28, and Ig lambda-2 chain C regions have not, to our knowledge, been previously associated with lung cancer." (PMID 28404947, 2017). "IGKC (8 fold in our study) up-regulated in lung cancer patients but no literature data was available for its interaction either with HIF or hypoxia." (PMID 23122428, 2012).
non-small cell lung carcinoma (5 papers, 2014 to 2025). A group of at least three distinct histological types of lung cancer, including non-small cell squamous cell carcinoma, adenocarcinoma, and large cell carcinoma. "A study of non-small cell lung cancer patient showed the overexpression of IGKC in stroma-infiltrating plasma cells." (PMID 38874510, 2024).
melanoma (3 papers, 2022 to 2025). A malignant, usually aggressive tumor composed of atypical, neoplastic melanocytes. "More recently, IGKC expression was associated with favorable response to immune checkpoint blockade in melanoma." (PMID 41149858, 2025). "Immunofluorescence staining was performed for the MM_Immune marker, IGKC, and the melanoma marker, Melan-A (MLANA), in formalin-fixed paraffin-embedded tissues of melanoma samples demonstrated an increased MM_Immune cell ratio in the NPD-pre group." (PMID 38505619, 2024).
colorectal cancer (2 papers, 2022 to 2025). A primary or metastatic malignant neoplasm that affects the colon or rectum. "IGKC has been defined as the first immune marker of response to cancer treatment in the context of chemotherapy in breast, non-small cell lung and colorectal cancer." (PMID 36012390, 2022).
gastric cancer (2 papers, 2017 to 2021). A primary or metastatic malignant neoplasm involving the stomach. "In the entire cohort, CD20+ B cells correlated strongly, and IGKC+ plasma cells correlated moderately to strongly, with CD3+, CD8+ and FoxP3+ cells respectively, with similar findings in esophageal and gastric cancer for CD20+ cells and stronger correlations for IGKC+ plasma cells in gastric cancer." (PMID 29069772, 2017).
ovarian carcinoma (2 papers, 2016 to 2022). A malignant neoplasm originating from the surface ovarian epithelium. "A study showed that plasma cell infiltration in epithelial ovarian cancer has a significant impact on tumor progression and prognosis, and high expression of IGKC is associated with good outcome." (PMID 36424614, 2022). "CD20 and IGKC expression was not prognostic but univariable Cox regression analysis revealed high CD138 expression to correlate with a significantly reduced overall survival (HR = 2.20; 95 % CI 1.34–3.55; p–0.001) as well as ovarian cancer-specific survival (HR = 1.95; 95 % CI 1.28–2.98; p = 0.002)." (PMID 27048364, 2016).
periodontal (2 papers, 2016). "In the present study, we found that HP, KNG1, A1AT and IGKC were differentially expressed in sera collected from periodontal patients." (PMID 27635317, 2016).
aortic stenosis (1 paper, 2022). Aortic valve stenosis is a aortic valve disease caused by the incomplete opening of the aortic valve. "Noteworthy, among these genes, immunoglobulin κ constant (IGKC) and IGKV1-12 are involved in antigenic responses, AXIN2 plays a well-known role in vascular calcification, and COL12A1 has been implicated in aortic stenosis and osteo-chondrogenic differentiation." (PMID 36437309, 2022).
atherosclerosis (1 paper, 2023). A disease characterized by the build-up of fatty material and calcium deposition in the arterial wall resulting in partial or complete occlusion of the arterial lumen. "We proposed that IGKC was involved in the inflammatory response in atherosclerosis and could be regarded as a novel biomarker for the formation of severe unstable arterial plaques." (PMID 37089432, 2023).
autism spectrum disorder (1 paper, 2024). A spectrum of developmental disorders that includes autism, and Asperger syndrome. "Notably, IGKC, known for its role in immunological and cancer-related processes, along with TMEM187 and SYTL4—genes associated with autism spectrum disorders—show interactions with key genes in these areas." (PMID 38778304, 2024).
autoimmune disease (1 paper, 2022). A disorder resulting from loss of function or tissue destruction of an organ or multiple organs, arising from humoral or cellular immune responses of the individual to their own tissue constituents. "Interestingly, several studies have reported that a combination of biomarkers, including IGKC and IGHA1, has good prognostic value in clear cell renal cell carcinoma and autoimmune diseases." (PMID 35646951, 2022).
Cachexia (1 paper, 2022). Severe weight loss, wasting of muscle, loss of appetite, and general debility related to a chronic disease. "B cells from patients with cachexia showed lower expression of MHC-II molecules (HLA-DRB5, HLA-DQA2) and higher expression of the immunoglobulins (IGHG2, IGHG3, IGKC), and genes involved in BCR signaling." (PMID 36376273, 2022).
Cirrhosis (1 paper, 2020). A chronic disorder of the liver in which liver tissue becomes scarred and is partially replaced by regenerative nodules and fibrotic tissue resulting in loss of liver function. "The other differentially expressed protein is IGKC that encodes the constant domain of kappa-type light chains for antibodies and was a member of the most overexpressed genes involved in antigen presentation in cirrhosis based on alcoholic and HCV." (PMID 33585012, 2020).
keratoconus (1 paper, 2016). A degenerative, structural disorder of the eye, characterized by a cone-shaped protrusion of the cornea. "Additionally, lipocalin (LCN), lysozyme C (LYZ), immunoglobulin alpha & kappa (IGKA & IGKC) and precursors to prolactin were deregulated in keratoconus." (PMID 27493978, 2016). "Albeit, recent studies have shown that matrix metalloproteinases MMP1 and 9, AZGP1, SFRP1, IGKC and cell adhesion molecules ICAM-1 and VCAM-1 to be specifically regulated in keratoconus, indicating their probable exclusive role in keratoconus." (PMID 27493978, 2016).
multiple myeloma (1 paper, 2021). "Among all dysregulated immune-related mRNAs, AEN, CD320, FABP5, and GPI were risk factors for multiple myeloma, while CXCL12, IGKC, NOD2, VCAM1, and WNT5A were protective factors for multiple myeloma." (PMID 34249967, 2021).
oral disorders (1 paper, 2025). "Although data on the role of salivary IGKC in oral disorders is lacking, its involvement could be linked to its role in antigen binding, antigen presentation, and immune response activation, all of which are relevant in RAS pathogenesis." (PMID 40869198, 2025).
prostate carcinoma (1 paper, 2024). A carcinoma that arises from epithelial cells of the prostate gland. "Our data suggested that IGKC could be a potential biomarker for prognosis of prostate cancer." (PMID 38874510, 2024).
schizophrenia (1 paper, 2023). A major psychotic disorder characterized by abnormalities in the perception or expression of reality. "It should also be admitted that among proteins significantly differed in quantitative measure, GPX3, IGKC, C2, and ATRN (adjusted p < 0.01) did not pass the significance level in the validation cohort of subjects with schizophrenia due to large deviation." (PMID 36747015, 2023).
Stroke (1 paper, 2024). Sudden impairment of blood flow to a part of the brain due to occlusion or rupture of an artery to the brain. "We found that tissue containing microglia nodules in MS had significant upregulated Ig genes (IGKC, IGHG1, IGHG2, and IGKV3-15) compared to tissue containing stroke nodules." (PMID 38396116, 2024). "Also, we found significantly upregulated expression of the Ig genes IGKC, IGHG1, IGHG2, and IGKV3-15 in MS nodule NAWM tissue as compared to stroke." (PMID 38396116, 2024).
triple-negative breast carcinoma (1 paper, 2024). An invasive breast carcinoma which is negative for expression of estrogen receptor (ER), progesterone receptor (PR), and human epidermal growth factor receptor 2 (HER2). "A previous retrospective immunohistochemical study demonstrated that tumor-infiltrating IgKC- and CD38-positive B-lymphocytes were associated with better prognosis in patients with early triple-negative breast cancer." (PMID 39456897, 2024).
Warthin tumor (1 paper, 2024). An adenoma characterized by an oncocytic, often papillary, epithelial component, dense lymphoid stroma, and cystic spaces. "On the other hand, the protein network detected in Warthin’s tumors (e.g., IGHG1, IGKC, IGHA1, and S100A9) was associated with immunological and inflammatory diseases." (PMID 39684268, 2024).
tumor (34 papers, 2012 to 2025). "A strong association between IGKC, tumor-associated plasma cell infiltration and improved prognosis was found by Yeong and co-workers in a retrospective cohort of 269 TNBC samples." (PMID 34298839, 2021). "In the epithelial pairwise comparison, we observed a significant upregulation of IGLC2 and IGKC, suggesting an active immune response initiated at the root epithelial cell population, where tumor proliferation appears to trigger EMT programming." (PMID 40950184, 2025). "Meanwhile, the downregulation of antigen presentation molecules (HLA-A/B) and immunoglobulin (IGKC) suggested potentially suppressed immune functions, facilitating tumor immune escape." (PMID 39944086, 2025). "T-C7 was scattered around T-C6 and was relatively high in immunoglobulins such as IGHG3 (immunoglobulin heavy constant gamma 3 involved in B-cell activation) and IGKC (immunoglobulin kappa constant), which are markers secreted by tumor-infiltrating B cells." (PMID 37124494, 2023). "Tumor-infiltrating plasmablasts and plasma cells were identified as the source of immunoglobulin kappa C (IGKC) expression using confocal microscopy." (PMID 34298839, 2021). "In particular, IGKC show a very distinctive increase, which was similar for both of the tumor entities examined." (PMID 30813269, 2019). "Only IGKC expression was found to differ significantly between histological subtypes, with higher expression in clear cell type tumours (p = 0.026)." (PMID 27048364, 2016). "Expression of IGKC as well as CD138 was significantly higher in primary tumours than in fallopian tubes (p = 0.004 and p = 0.001, respectively)." (PMID 27048364, 2016). "Strikingly, it showed that IGHG4 and IGKC were predominantly expressed in HER2neg TNBC group (in tumor tissues containing tumor cells and mesenchymal cells), whereas APOD and MUCL1 were highly expressed in HER2low group, which were consistent with the scRNA-seq data." (PMID 36998014, 2023). "B cells from COPD and cancer shared biological functions, and tumor‐infiltrating B cells overexpressed genes (IGHG1‐4, IGKC, IGHA1) consistent with COPD." (PMID 41377765, 2025). "Then, we verified the expressions of IGHG4, IGKC, APOD and MUCL1 at the protein level in tumor sections of clinical TNBC patients (HER2low, n = 5 vs. HER2neg, n = 5) by IF staining." (PMID 36998014, 2023). "IGKC, SCGB1A1 HSPB1, and FCGR3A were found to be differentially expressed in normal tissue compared with tumor and metastasis." (PMID 37335089, 2023). "The results showed that tumor cells in metastatic LN expressed high levels of IGLC2, IGHG4, and IGKC, and GO analysis showed various immune-related signaling pathways." (PMID 36569924, 2022). "Tumor‐infiltrating CD8‐positive ICs, FOXP3‐positive ICs, CD20‐positive ICs, and IGKC‐positive ICs generally had positive correlations with each other." (PMID 33506656, 2021). "Of note, tumor‐infiltrating CXCL13‐positive ICs were positively correlated with CD20‐positive ICs and IGKC‐positive ICs, suggesting that the tumor infiltration of B cells and plasma cells was due to CXCL13 production by TILs." (PMID 33506656, 2021). "The numbers of tumor‐infiltrating CD20+ immune cells (ICs) (p < 0.001), IGKC+ICs (p = 0.023), and CXCL13+ ICs (p = 0.044) were significantly higher in the high HER2‐AAb group than in the low HER2‐AAb group." (PMID 33506656, 2021). "Immunohistochemistry results in 20 surgically resected LACs and adjacent normal tissues showed that IGKC, AAT and SH3BGRL3 were more highly expressed in tumor cells as compared to non-tumor tissues." (PMID 28404947, 2017). "Immunohistochemical expression of immunoglobulin kappa C (IGKC), CD20 and CD138 was analysed in tissue microarrays with tumours from 154 incident cases of EOC from two pooled prospective population-based cohorts." (PMID 27048364, 2016).